CYP1B1 (cytochrome P450 family 1 subfamily B member 1)
Diseases named in the same sentence as CYP1B1 in open-access papers (continued):
Sharing a sentence is not in itself a finding about the gene and the disease.
glaucoma (continued). "Obviously, further studies are needed to elucidate the possible role of CYP1B1 variations such as R48G in juvenile glaucoma with goniodysgenesis." (PMID 19668597, 2009). "To date, about 23 loci have been linked to different types of glaucoma, and four genes, myocilin (MYOC), optineurin (OPTN), cytochrome P450 1B1 (CYP1B1), and WD repeat domain 36 (WDR36), have been identified as glaucoma causing genes." (PMID 19668597, 2009). "The relatively large contribution of CYP1B1 to glaucoma among Iranians suggested by the results of these studies prompted us to further investigate its role in a larger cohort of POAG patients which included late-onset patients." (PMID 19096718, 2008). "MYOC, OPTN, WDR36, and CYP1B1 have all been identified in a relatively small percentage of patients with various types of glaucoma, and it remains possible that these genes are abnormal with a small percentage of PEG patients." (PMID 18246027, 2008). "We aimed to further investigate the role of CYP1B1 in a larger cohort of primary open angle glaucoma (POAG) patients which included late-onset patients." (PMID 19096718, 2008). "Previously known and novel mutations detected in the CYP1B1, MYOC, and OPTN genes in primary open-angle glaucoma patients." (PMID 17563717, 2007). "For example, CYP1B1 exhibited high expression, particularly in the ICB and RC, aligning with its known role in steroid metabolism and its association with ocular diseases such as glaucoma." (PMID 40505410, 2025). "Notably, CYP1B1 had very high expression particularly in the ICB and RC, aligned with its known role in steroid metabolism and its association with glaucoma." (PMID 40505410, 2025). "In addition, the retina- and glaucoma-related ocular tissues, i.e., anterior chamber angles and cornea, were similar in cyp1b1-KO and wildtype siblings." (PMID 34208498, 2021). "The secondary childhood glaucoma cases showed diverse phenotypes and genotypes (n = 8): Peters anomaly was linked with CYP1B1 mutations in two cases (25%), no mutation was found in one case (13%)." (PMID 35011756, 2021). "In glaucoma, characterized CYP1B1 mutations have not been properly investigated in astrocytes, microglia, oligodendrocytes, or other neural stromal cells." (PMID 32626511, 2020). "Here, we focus on the correlation between CYP1B1 and the development of glaucoma and cancer." (PMID 32626511, 2020). "The genetic heterogeneity present in PCG, along with the frequent incomplete penetrance and variable expressivity, even in patients with null CYP1B1 genotypes, strongly indicates the participation of modifier genetic and/or environmental factors in the pathogenicity of this type of glaucoma." (PMID 30657791, 2019). "We investigated the molecular basis of the variable phenotypes resulting from the defects in CYP1B1 by using subclones of 23 CYP1B1 mutants reported in glaucoma patients, in a cell based system by measuring the dual activity of the enzyme to metabolize both retinol and 17β-estradiol." (PMID 27243976, 2016). "COL1A1 analysis of the complete coding region by Sanger sequencing was then carried out in an independent cohort of 24 German patients diagnosed with congenital/early onset glaucoma that were found negative for mutations in CYP1B1 and MYOC genes." (PMID 27484908, 2016). "Detecting mutations helps to determine mode of inheritance; for example, mutations in CYP1B1 and LTBP2 cause recessive traits, whereas glaucoma caused by other known genes may be inherited in a dominant fashion." (PMID 24665880, 2014). "Furthermore, disease alleles were observed for other autosomal dominantly inherited degenerative diseases of sensory function, including retinitis pigmentosa (SEMA4A, RP1), deafness (MYO1A), glaucoma (CYP1B1, OPTN, WDR36), and keratoconus (VSX1)." (PMID 25333069, 2014). "CYP1B1 mutation screening was performed in 119 control individuals with no family history of glaucoma." (PMID 23922489, 2013).
glaucoma (continued). "Among the five known glaucoma-causing genes– MYOC (myocilin), CYP1B1 (cytochrome P450, family 1, subfamily B, polypeptide 1), OPTN (optineurin), WDR36 (WDR36), and LTBP2 (latent transforming growth factor beta binding protein 2)–all except WDR36 were identified in three of the studies." (PMID 22312193, 2012). "However, further in-vivo studies on animal models are necessary to provide additional supporting evidence for CYP1B1 mediated MYOC upregulation as a molecular basis for glaucoma pathogenesis." (PMID 23028769, 2012). "Recently, another gene, CYP1B1, has been suggested to modify the glaucoma phenotype." (PMID 22876119, 2012). "Myocilin (MYOC), a candidate gene for juvenile and adult onset forms of primary open angle glaucoma, may have been involved with CYP1B1 through a digenic mechanism in a glaucoma family of East Indian (Guyanese) origin." (PMID 21572728, 2011). "Four genes, trabecular meshwork inducible glucocorticoid response (MYOC/TIGR), human dioxin-inducible cytochrome P450 (CYP1B1), optineurin (OPTN), and WD repeat domain 36 (WDR36), have been identified as glaucoma-causing genes, with MYOC being the first identified POAG gene." (PMID 21655360, 2011). "Recently, another gene CYP1B1, indeed, has been suggested to modify the glaucoma phenotype." (PMID 21655360, 2011). "In addition to the identified genetic loci linked to POAG, other genetic factors e.g. OPA1, Apolipoprotein E, CYP1B1, E-cahderin, OPTC have been reported to elevate the risk of retinal degeneration characteristic of glaucoma." (PMID 20565898, 2010). "Little improvement in vision (light perception only) following glaucoma surgery was observed in all five cases with heterozygous Ter@223 mutation whereas other patients with homozygous/compound heterozygote CYP1B1 mutations showed no improvement at all." (PMID 19536304, 2009). "Thus, it is worth examining the association of the CYP1B1 variant with POAG among African and/or Afro-Americans with incidence of glaucoma similar to that performed in prostate cancer." (PMID 18483560, 2008). "The aim of the current study was a similar evaluation of PEG patients for the presence of mitochondrial abnormalities and nuclear gene mutations associated with various types of glaucoma (MYOC, OPTN, WDR36, and CYP1B1) and certain inherited optic neuropathies (OPA1 and OPA3)." (PMID 18246027, 2008). "Mutations in the CYP1B1, MYOC, OPTN, and WDR36 genes result in glaucoma." (PMID 17563717, 2007). "However, in recent years it has been observed that CYP1B1 also could play an important role in the development of adult glaucoma." (PMID 38241218, 2024). "In addition, CYP1B1 is perhaps one of the most well-known P450s among eye researchers as, in 1997, CYP1B1 was identified as a causative gene for primary congenital glaucoma (PCG), the major glaucoma type in the pediatric population." (PMID 36914277, 2023). "In Nouakchott, a white Maure family blinded by glaucoma carried a homozygous mutation in CYP1B1 that was not present in other families and results in an early terminating codon at position 150 downstream of CYP1B1, resulting in a heavily shortened CYP1B1." (PMID 35407656, 2022). "Therefore, alteration of CYP1B1 expression may suggest a therapeutic benefit for multiple diseases such as glaucoma and cancer." (PMID 32626511, 2020). "We hypothesize that the genotype of CYP1B1 in an individual, activity of the expressed gene product towards its substrate (retinol and estradiol), along with other, yet undescribed, factors finally determine the manifestation of the glaucoma phenotype." (PMID 27243976, 2016). "Hence any mutation in CYP1B1 that reduces its 17β estradiol metabolizing activity might lead to MYOC upregulation, which in turn might play a role in glaucoma pathogenesis." (PMID 23028769, 2012). "Higher ROS generation by Val432 in CYP1B1 might lead to apoptotic change that leads to glaucoma." (PMID 18483560, 2008).
glaucoma (continued). "Since glaucoma eventually results from defects in the RGCs due to increased sensitivity to IOP changes, the influence of Cyp1b1 on the development of RGCs under normal and stressed conditions, such as elevated ocular pressure, was investigated." (PMID 38755526, 2024). "Later, CYP1B1 was found to be a modifier gene for primary open-angle glaucoma (POAG), the major glaucoma type in the adult population." (PMID 36914277, 2023). "Consequently, CYP1B1 expression, which is elevated during AhR activation, alters the biosynthesis of critical metabolites as well as metabolic pathways that may lead to the initiation and/or progression of glaucoma." (PMID 35743162, 2022). "In contrast to humans, we did not observe ocular glaucoma-related histological defects associated with complete cyp1b1 LoF in zebrafish, which might be due to developmental species differences and shows that zebrafish are not adequate to model cyp1b1-associated glaucoma." (PMID 34208498, 2021). "The variable phenotype expression of glaucoma, even in families, cannot be explained with a digenic mechanism between MYOC and CYP1B1." (PMID 23922489, 2013). "However, the exact mechanism by which CYP1B1 contributes to glaucoma remains unknown." (PMID 22509109, 2012). "myocilin (MYOC), optineurin (OPTN), WDR36 and neurotrophin-4 (NTF4) in primary open angle glaucoma (POAG) and CYP1B1 and LTBP2 in congenital and developmental glaucomas." (PMID 21150032, 2011). "Analysis of the combined RNA-Seq and ChIP-Seq data showed that the transcription of several of the differentially expressed genes with roles in TM, IOP, and glaucoma, were directly regulated by GLIS1 and included MYOC, LTBP2, CHI3L1, HMGA1, CYP1B1, and LOXL1-4." (PMID 34385434, 2021). "Although it does not encode a transcription factor, alterations in CYP1B1 expression have also been shown to cause ASD and are associated with glaucoma." (PMID 34440692, 2021). "In addition to these ECM and adhesion-related genes, transcriptome analysis showed that GLIS1 impacts the expression of several other TM-, IOP-, and glaucoma-related genes, including MYOC and CYP1B1." (PMID 34385434, 2021). "Thus, our bioinformatic analysis revealed upregulation of two CYP enzymes, CYP1B1 and CYP39A1, in TM cells model of glaucoma pathogenesis." (PMID 34356513, 2021). "On the other hand, a balanced expression of CYP1B1 in either glaucoma or cancer has not been investigated." (PMID 32626511, 2020). "Our hypothesis is supported by the reported occurrence of two glaucoma patients in a family: (i) a PCG patient carrying F261L and R355fsX69 in CYP1B1, and (ii) an ocular hypertensic patient carrying a single mutation (F261L) in CYP1B1." (PMID 27243976, 2016). "We detected a high percentage of mutations in CYP1B1, which causes glaucoma in families with PCG but not in other glaucoma phenotypes." (PMID 23922489, 2013). "This cytochrome has been proposed to participate in iridocorneal angle development, thus alteration of CYP1B1 catalytic activity could impair the morphogenesis of the outflow angle, leading to IOP elevation and glaucoma." (PMID 19234632, 2009). "In addition, we analysed genes that have been previously identified as candidate genes in glaucoma (OPTN, OPA1, CYP1B1)." (PMID 19754948, 2009). "CYP1B1 mutations are also present in certain families where PCG and primary open-angle glaucoma (POAG) coexist, in non-Mendelian POAG cases, and in monogenic anterior segment dysgenesis like Peters’ anomaly and Rieger’s anomaly." (PMID 19234632, 2009). "However, the phenotypes of these homozygous knockout mice are rather mild in relation to glaucoma, indicating that these Cyp1b1-knockout model mice are not suitable for studying the heterozygous phenotype." (PMID 39158757, 2024).
glaucoma (continued). "Melatonin synthesis in the eye, acting as a CYP1B1 inhibitor, and its modulation of retinal functions, such as dopamine synthesis, photoreceptor activity, and IOP regulation, suggest a potential link between CYP1B1-mediated retinoid metabolism, melatonin signaling, and glaucoma." (PMID 38671671, 2024). "No glaucoma-related phenotypes were observed in cyp1b1 mutants." (PMID 34208498, 2021). "In accordance with our results, 48-hpf zebrafish embryos with MO cyp1b1 knockdown did not present glaucoma; they only manifested mild ocular phenotypes that recovered by the larval stage and presented minimal effects on zebrafish craniofacial development at 96 hpf." (PMID 34208498, 2021). "In addition, we identified several transcriptional targets of GLIS1 in TM cells that previously have been implicated in TM-related functions, IOP homeostasis, and ocular hypertension/glaucoma, including MYOC, ADAMTS10, LTBP2, LOXL1, TGFBR3, CYP1B1, and EFEMP15,28,43,44." (PMID 34385434, 2021). "Interestingly, her brother, who inherited the same CYP1B1 genotype and did not present the PITX2 variant, was diagnosed with bilateral infantile glaucoma at the age of ten years." (PMID 30657791, 2019). "Thus, it is important to screen other glaucoma-associated loci and genes for involvement in congenital glaucoma in cases that are either negative or heterozygous for MYOC, CYP1B1, and FOXC1 mutations to have better insight into the disease pathogenesis." (PMID 23378721, 2013). "The two coding exons of CYP1B1 were analyzed with PCR and sequencing in 45 index patients with POAG, 25 index patients with PCG, 21 index patients with JOAG, four index patients with Axenfeld-Rieger syndrome (ARS), and seven index patients with other types of glaucoma." (PMID 23922489, 2013). "However, gross examination of the eyes of these CYP1B1-/-mice neither showed any evidence of glaucoma nor any systemic abnormalities suggesting that CYP1B1 is not required for mammalian development." (PMID 21572728, 2011). "Because MYOC variants have an autosomal dominant inheritance and CYP1B1 variants have an autosomal recessive inheritance, a multi‐generation family history of glaucoma could support the presence of MYOC variants, whilst an absence of family history could suggest CYP1B1 variants." (PMID 39929609, 2025). "Therefore, CYP1B1 expression, which is increased by AHR, alters production of critical metabolites and metabolic pathways that may lead to the development and/or progression of glaucoma." (PMID 35295218, 2022). "Other genes, including FOXC1, CYP1B1, LMX1B and MYOC were not expressed substantially in any neural retina cell classes, consistent with their proposed role predominantly in the anterior segment with mutations leading to high intraocular pressure, a major risk factor for glaucoma." (PMID 32555229, 2020). "Thus the experimental observations are consistent with our proposed hypothesis that mutant CYP1B1, lacking the 17β estradiol metabolizing activity, can cause MYOC upregulation, which might have a potential implication in glaucoma pathogenesis." (PMID 23028769, 2012). "Interestingly, carriers of MMP-related genes demonstrated a twofold increase in the number of glaucoma surgeries per eye compared to non-carriers (1.98 surgeries vs. 0.88 surgeries), and both groups underwent fewer surgical interventions compared to individuals with null CYP1B1 genotypes." (PMID 38891949, 2024). "The expression levels of hub genes were significantly correlated with the expression levels of multiple glaucoma-related genes, among which HSPA8 was significantly negatively correlated with CYP1B1 (Pearson r = − 0.48) and RPL15 was significantly positively correlated with WDR36 (Pearson r = 0.58)." (PMID 37968618, 2023).
primary congenital glaucoma (61 papers, 2007 to 2026). "CYP1B1 is the most commonly identified genetic cause of primary congenital glaucoma (PCG), causing 15–35% of PCG in European studies, and up to 100% of PCG in some ethnic groups." (PMID 41011222, 2025). "CYP1B1 variants were associated with region and population-specific prevalence ranging from 5% to 86% among those with primary congenital glaucoma." (PMID 38386645, 2024). "Homozygous or compound heterozygous germline mutations in the CYP1B1 gene are linked to the recessive syndrome primary congenital glaucoma (GLC3A; OMIM #231300)." (PMID 37762649, 2023). "CYP1B1 was first identified as a causative gene of primary congenital glaucoma, and CYP1B1 mutations have also been identified in POAG." (PMID 37968618, 2023). "In fact, mutations of the human CYP1B1 gene are the most common causes of autosomal recessive primary congenital glaucoma in the world." (PMID 36230892, 2022). "The present study was focused on identifying the high-risk missense deleterious variants of the CYP1B1 gene that are associated with primary congenital glaucoma (PCG) through comparative in silico approaches." (PMID 36518267, 2022). "Primary congenital glaucoma is an ocular disorder inherited in an autosomal recessive manner, where CYP1B1 was the first gene to be described as the causative agent for PCG and the most commonly mutated gene in PCG." (PMID 35407656, 2022). "The aim of this work was to assess the polymorphism of the CYP1B1 geneamong West Siberian patients with primary congenital glaucoma." (PMID 35087999, 2020). "Plásilová M., Stoilov I., Sarfarazi M., Kádasi L., Feráková E., Ferák V.Identification of a single ancestral CYP1B1 mutation in SlovakGypsies (Roms) affected with primary congenital glaucoma." (PMID 35087999, 2020). "Chouiter L., Nadifi S. Analysis of CYP1B1 gene mutations in patientswith primary congenital glaucoma." (PMID 35087999, 2020). "Mashima Y., Suzuki Y., Sergeev Y., Ohtake Y., Tanino T., Kimura I.,Miyata H., Aihara M., Tanihara H., Inatani M., Azuma N., Iwata T.,Araie M. Novel cytochrome P4501B1 (CYP1B1) gene mutationsin Japanese patients with primary congenital glaucoma." (PMID 35087999, 2020). "Studies have shown that CYP1B1 is a causative gene in primary congenital glaucoma, and that the phenotype of Cyp1b1-/- mouse model resembled glaucomatous human eyes." (PMID 30574417, 2018). "Mutations in the CYP1B1 gene are currently the main known genetic cause of primary congenital glaucoma (PCG), a leading cause of blindness in children." (PMID 28448622, 2017). "This has been found to be true and CYP1B1 mutations have been observed in a majority of primary congenital glaucoma (PCG) patients from all over the globe." (PMID 26997841, 2015). "Mutations in CYP1B1 are also associated with childhood blindness due to primary congenital glaucoma (PCG)." (PMID 25329831, 2014). "CYP1B1 has been implicated in primary congenital glaucoma with autosomal recessive mode of inheritance." (PMID 23028769, 2012). "CYP1B1 single nucleotide polymorphisms and mutations detected in 20 probands with primary congenital glaucoma." (PMID 20664688, 2010). "The cytochrome p450 family 1 subfamily B (CYP1B1) gene is a well known cause of autosomal recessive primary congenital glaucoma." (PMID 21139974, 2010). "This study was planned with the aim to identify the mutation profile of CYP1B1 in North Indian primary congenital glaucoma (PCG) patients." (PMID 19536304, 2009). "This study was conducted to investigate the mutation spectrum of the cytochrome P450 gene (CYP1B1) in Chinese patients with primary congenital glaucoma (PCG)." (PMID 19247456, 2009).